TCN2 (transcobalamin 2)
Diseases named in the same sentence as TCN2 in open-access papers (continued):
Sharing a sentence is not in itself a finding about the gene and the disease.
hyperthyroidism (1 paper, 2022). Overactivity of the thyroid gland resulting in overproduction of thyroid hormone and increased metabolic rate. "In the present study, the downregulation of Tcn2, Btd, Proc, Proz, Gc, and Afm indicated the usage of vitamins might be inefficient in thyrotoxicosis mice, which is not only related to hyperthyroidism related complications but also aging related diseases." (PMID 35720307, 2022).
leukopenia (1 paper, 2022). "In addition, several SNPs in TCN2, CUBN, and MUT genes appeared to be more prone to the occurrence of multiple clinical manifestations, including drug resistance, hypoproteinemia, and leukopenia in PTB patients." (PMID 36275653, 2022).
liver disease (1 paper, 2024). "There are multiple molecular mechanisms that mediate VB12 elevation, including the elevation of transporter proteins in neoplasms, massive release from hepatic reservoirs, decreased transcobalamin 2 production in liver disease or reduced transcobalamin 2 filtration in kidney disease." (PMID 39252806, 2024).
lung carcinoma (1 paper, 2024). "The identification of LTB4R, LTBP4, MPI, and TCN2, in conjunction with PSMA4, highlights the intricate heterogeneity of lung cancer and underscores the necessity for tailored therapeutic strategies." (PMID 39529882, 2024).
lupus nephritis (1 paper, 2024). Glomerulonephritis in the context of systemic lupus erythematosus. "These in vivo results suggest the importance of TCN2 for germinal center-mediated immune activity, as seen in the kidneys of patients with lupus nephritis." (PMID 39493449, 2024).
lymphoma (1 paper, 2024). A malignant (clonal) proliferation of B- lymphocytes or T- lymphocytes which involves the lymph nodes, bone marrow and/or extranodal sites. "later determined that TCN2 could not only drive proliferation of human erythroleukemic and murine lymphoma cell lines in vitro, but antibody blockade of its receptor could also effectively inhibit cellular growth." (PMID 39493449, 2024).
preeclampsia (1 paper, 2025). Preeclampsia is a hypertensive disorder of pregnancy that is characterized by new-onset hypertension with proteinuria presenting after 20 weeks of gestation, and depending on mild or severe forms may initially present with severe headache, visual disturbances, and hyperreflexia. "Transcobalamin (TCN2) transports cobalamin (vitamin B12) from the bloodstream, and a recent meta-analysis showed that women with preeclampsia had significantly lower cobalamin concentrations than normotensive pregnant women (DMR3)." (PMID 41286963, 2025).
sarcoma (1 paper, 2024). A usually aggressive malignant neoplasm of the soft tissue or bone. "Survival analysis using the Survival Genie web-based platform indicated that increased intratumoral TCN2 expression was associated with better overall survival in both OSA (TARGET-OS) and sarcoma (TCGA-SARC) datasets." (PMID 39493449, 2024). "The Survival Genie web-based platform was then used to associate expression of TCN2 and AHSG with overall survival in publicly available OSA (TARGET-OS) and sarcoma (TCGA-SARC) bulk tumor RNA-sequencing datasets." (PMID 39493449, 2024). "Analysis of the TCGA-SARC dataset identified 177 patients with low and 82 patients with high expression of TCN2 in sarcoma primary tumors." (PMID 39493449, 2024).
Seizure (1 paper, 2023). A seizure is an intermittent abnormality of nervous system physiology characterized by a transient occurrence of signs and/or symptoms due to abnormal excessive or synchronous neuronal activity in the brain. "For example, the plasma level of TCN2 was significantly increased in the newly diagnosed epileptic seizure patients and long-standing grand mal epileptic patients." (PMID 37684700, 2023).
staphylococcus aureus infection (1 paper, 2024). An infectious process in which the bacteria Staphylococcus aureus is present. "TCN2 deficiency was also previously associated with abnormal granulocyte function and limited antimicrobial response to Staphylococcus aureus infection." (PMID 39493449, 2024).
thyroid cancer (1 paper, 2024). "Considering the literature data, the elevated level of TCN2, a co-factor taking part in the kobalamin (vitamin B12) transport, was associated with the increased risk of thyroid cancer development, which supports the outcome obtained in the present study." (PMID 39456618, 2024).
thyrotoxicosis (1 paper, 2022). A hypermetabolic syndrome caused by the elevation of thyroid hormone levels in the serum. "In the present study, the abundance of Biotinidase (Btd), Transcobalamin II (Tcn2), vitamin D binding protein (VDBP, Gc), Afamin (Afm), Vitamin K-dependent protein C (Proc), and Vitamin K-dependent protein Z (Proz) were downregulated in thyrotoxicosis mice." (PMID 35720307, 2022).
viral infection (1 paper, 2023). "Additionally, TCN2 and C1QA showed predominant expression in macrophages, suggesting the involvement of macrophage activation in viral infection." (PMID 37942334, 2023). "Notably, four markers (C4BPB, TCN2, SMD9L, and C1QA) displayed an AUC exceeding 0.8, with a combined AUC of 0.95, suggesting their potential to serve as early markers for viral infection and severe disease." (PMID 37942334, 2023).
cancer (12 papers, 2014 to 2025). A tumor composed of atypical neoplastic, often pleomorphic cells that invade other tissues. "TCN2 plays a critical role in reversing the hypoxia microenvironment caused by cancer cells, which explains its existence as a protective factor for CSCC in this study." (PMID 36057587, 2022). "Indeed, a prospective assessment of the association between the overexpression of TCN1/TCN2/CD320 or high loads of TCI/TCII/TCII-R on immunohistological analyses of cancer tissues and their resistance to treatment, or for the prognosis, will help to adapt the treatment and survey strategy." (PMID 35631199, 2022). "The potential involvement of TCN2 in iron metabolism dysregulation in cancer offers a novel perspective on cancer cell biology." (PMID 39529882, 2024). "High TCI and TCII levels are observed in tumor samples, which argues for an intratumoral synthesis of transcobalamins, supported by the overexpression of TCN1 and TCN2 in cancers cells." (PMID 35631199, 2022). "Other cancer types should now be investigated for this parameter, as well as for TCN2 and CD320 expression levels." (PMID 35631199, 2022). "The authors also suggested the possibility of impaired TCN2 elimination from the circulation in patients with cancer." (PMID 36364737, 2022). "An open question is whether vitamin B12 binders (TCN1 and TCN2) are upregulated to the same degree in patients with cancer." (PMID 36364737, 2022). "Additionally, TCN2, crucial for vitamin B12 transport, may indicate altered metabolic requirements of cancer cells." (PMID 40227838, 2025). "Thus, TCN2 regulation has an important role in dictating the phenotype of the cancer cell." (PMID 35631199, 2022). "Furthermore, TCN2 downregulation in glioblastoma cell lines decreased cobalamin intracellular concentration in hypoxic conditions, stimulating the epithelial–mesenchymal transition (EMT) process, and promoting migratory and invasive properties, and cancer stem cell (CSC) differentiation." (PMID 35631199, 2022).
tumor (6 papers, 2021 to 2026). "Considering the previous publication’s note regarding isolation of these B lymphocytes from confirmed TLSs in one naive primary tumor, we also associated the highest % of TCN2+ Myeloid cells (relative to all Myeloid cells) with intratumoral TLS formation." (PMID 39493449, 2024). "These preliminary results, however, suggest the necessity for elevated TCN2+ Myeloid cells for B lymphocyte proliferation in the OSA tumor microenvironment." (PMID 39493449, 2024). "Exogenous TCN2 may be critical to drive the robust expansion and lymphocytic proliferation necessary for enhanced anti-tumor immune responses in these patients." (PMID 39493449, 2024). "Importantly, while only OS-6 contained a substantial number of CD320+ Plasmocytes and B cells, this primary tumor also measured the greatest percentage (%) of TCN2+ Myeloid cells (relative to all Myeloid cells) at 38.68%." (PMID 39493449, 2024). "While only preliminary, both TCN2+ Myeloid and CD320+ Plasmocytes and B cells were identified by scRNA-seq analyses of OSA tumor specimens." (PMID 39493449, 2024).
TCN2 also shares sentences with these, for which no sentence is quoted: infection (47 papers); Chagas disease (19); co-infection (4); parasitemias (3); Diabetes (2); Down syndrome (2); Failure to thrive (2); metabolic disorder (2); myelodysplastic syndrome (2); schizophrenia (2); Transcobalamin deficiency (2); acute respiratory distress syndrome (1); Alzheimer disease (1); anencephaly (1); autism (1); autoimmune disorders (1); autoimmune hemolytic anemia (1); cardiac disease (1); cardiomyopathy (1); cardiovascular diseases (1); cataract (1); celiac disease (1); chronic lymphocytic leukemia (1); cleft palate (1); cobalamin deficiency (1); cognitive decline (1); Cognitive impairment (1); colon cancer (1); congenital heart defects (1); dermatomyositis (1).
A further 54 diseases each share a sentence with TCN2 in 1 paper.